GFAP (glial fibrillary acidic protein)
Diseases named in the same sentence as GFAP in open-access papers (continued):
Sharing a sentence is not in itself a finding about the gene and the disease.
amyloid (continued). "In addition, plasma glial fibrillary acidic protein (GFAP), an indicator of reactive astrogliosis often associated with brain Aβ plaques, has also been proposed as an early marker for amyloid pathology." (PMID 38750570, 2024). "Interestingly, we observed lower GFAP expression in Aβ-/tau+ individuals compared to Aβ+/tau+ individuals, suggesting that GFAP is more closely linked to amyloid than tau pathology." (PMID 39580758, 2024). "In addition, we detected the age-dependent presence of activated microglia and GFAP-reactive astrocytes around Aβ plaques, starting at 4 months, indicating that amyloidosis-associated neuroinflammation occurred at an early stage in App-KI mice." (PMID 33183323, 2020). "Finally, given that neuroinflammation and Alzheimer's disease pathology have been suggested to be closely related, a mediation analysis of the effect of GFAP in the association between amyloid and tau, and the association between tau and cognitive performance and decline was studied." (PMID 38940331, 2024). "Also, early markers of amyloid deposition such as p‐tau217, p‐tau213, and GFAP may be more closely linked with cognitive changes in the early phases of the disease." (PMID 38623387, 2024). "We found that propionate treatment phenocopied ABX treatment, in that it reduced GFAP+ astrocytosis and amyloidosis." (PMID 40359034, 2025). "While several studies report that plasma GFAP correlates more strongly with the amyloid burden compared to CSF GFAP, our data emphasize the potential of CSF GFAP to reflect tauopathy-related processes." (PMID 40943059, 2025). "The Lumipulse G GFAP assay significantly differentiated (p < 0.05) between the amyloid accumulation and non-amyloid accumulation groups, as classified based on the CSF Aβ test." (PMID 40943059, 2025). "Notably, subpial TTR amyloid deposits are associated with astrocytosis, highlighting that astrocytic activation and damage are crucial features of ATTRv pathology and may significantly contribute to the observed elevation in serum GFAP concentrations." (PMID 40232501, 2025). "Comparison across anti‐amyloid antibodies indicates utility of p‐tau and GFAP as biomarkers of amyloid plaque removal while NfL and tau PET seem unsuitable as consistent indicators of clinical efficacy." (PMID 39887500, 2025). "This mutual relationship suggests a close, reciprocal link between early amyloid deposition and GFAP‐related astrogliosis, reinforcing the notion of a tightly coordinated interaction between glial responses and amyloid pathology in the early stages of AD." (PMID 40747577, 2025). "GFAP partially mediated the relationship between amyloid‐PET and tau‐PET (15.3%) and amyloid‐PET and plasma pTau‐217 (42.1%)." (PMID 39535359, 2025). "The superior discriminative performance of GFAP for tau pathology (AUC = 0.86) over amyloid pathology (AUC = 0.72) implies that astrocyte reactivity is more closely linked to tau-driven neuronal injury." (PMID 40943059, 2025). "Our findings on GFAP, marker of astrocytic activation, which can be a response to amyloid plaque formation in AD41, align with evidence reporting its association with the progression from MCI to dementia." (PMID 41276530, 2025). "In the early stages of AD, amyloid plaques are surrounded by activated astrocytes, increasing GFAP expression, which correlates with disease severity." (PMID 40690136, 2025). "GFAP concentrations were elevated in higher levels of amyloid neuropathology (CERAD frequent, Thal phase 4 or higher), but the fold-change over higher ADNC and Braak stages was modest compared to p-tau217 (eFigure 6 in Supplement 1)." (PMID 39928343, 2025). "While numerous studies have assessed the viability of elevated plasma GFAP as a biomarker for AD and amyloid pathology, few have focused on changes in GFAP expression in brain." (PMID 39580758, 2024).
amyloid (continued). "The significant interaction between GFAP protein levels and amyloid status on longitudinal cognition further supports the role of GFAP in modulating the cognitive effects of amyloid pathology." (PMID 39580758, 2024). "Numerous studies have assessed the viability of elevated plasma GFAP as a biomarker for AD and amyloid pathology." (PMID 39580758, 2024). "GFAP also explains, in part, the effect of amyloid pathology on tau accumulation and of tau pathology on subsequent cognitive decline." (PMID 38940331, 2024). "NLY01, an exendin-4 derivative, administered using doses of 1 or 10 mg/kg starting at the age of 3 months, for a total of 4 months, resulted in improved spatial learning and attenuated hippocampal amyloid plaque burden and GFAP expression in 5XFAD mice." (PMID 39216535, 2024). "This relationship remained statistically significant even after adjusting for astrocytic transcript fraction, underscoring the robust upregulation of GFAP within astrocytes in the presence of amyloid pathology." (PMID 39580758, 2024). "Combining GFAP and ptau-181 together was the best model to predict brain amyloid status across all participants (AUC = 0.86) or within cognitively impaired participants (AUC = 0.93); adding NfL as an additional predictor only had a marginal improvement." (PMID 37924152, 2023). "Given that severe amyloid pathology was observed in the hippocampus by 4G8 staining, we focused on GFAP expression changes in the hippocampus." (PMID 36899916, 2023). "Morphologically, reactive astrocytes hypertrophy, increase expression of cytoskeletal proteins such as GFAP and vimentin, and are found surrounding amyloid plaques where their processes extended into the plaque core." (PMID 37533101, 2023). "The coverages of amyloid plaques and the ratio of GFAP coverage to amyloid plaque coverage were significantly higher in early- and advanced-stage APP/PS1 mice than in their age-matched WT littermates (p < 0.05 for both)." (PMID 37433857, 2023). "Removal of APOE4 from a mouse model of amyloidosis reduces GFAP reactivity in male mice, while single-nuclei RNA sequencing in a mouse model of tauopathy has revealed that numerous DAA genes such as Clu and Vim are reduced." (PMID 36922879, 2023). "Apolipoprotein E and glial fibrillary acidic protein are known biomarkers of AD; the first plays a role in early amyloidosis, cholesterol metabolism, and inflammatory response, and the latter is an established marker of glial-specific neuroinflammation." (PMID 35944844, 2022). "Our co-staining results confirm that amyloid plaques were closely surrounded by GFAP-positive astrocytes in the APP/PS1 brain." (PMID 35895177, 2022). "Glial fibrillary acidic protein (GFAP) is a marker of astrogliosis and is associated with amyloidosis in AD, and its expression is correlated with the density of Aβ plaques." (PMID 35306613, 2022). "Such gliosis can be identified by staining of glial fibrillary acidic protein (GFAP) in reactive astrocytes surrounding amyloid plaques." (PMID 35235058, 2022). "There was a striking increase in GFAP expression in the hilus region of the dentate gyrus as well as around amyloid plaques (yellow arrow)." (PMID 33185010, 2021). "A detailed analysis of the treated brains showed that the immunePEG liposome-mediated reduction in amyloidosis correlated with lower levels of glial fibrillary acidic protein (GFAP) and reactive glia (GFAP-positive cells)." (PMID 32523525, 2020). "Insoluble extracellular Aβ deposits forming amyloid plaques and accumulation of ApoE and GFAP in the brain are all key histopathological hallmarks of AD." (PMID 32082134, 2019). "As previously reported, we observed that amyloid plaques were surrounded by GFAP-positive astrocytes and Iba1-positive microglia." (PMID 29922152, 2018).
amyloid (continued). "3xTg mice were injected at 3–4 months with AAV-GFP or AAV-SOCS3 + AAV-GFP (3xTg-GFP and 3xTg-SOCS3 mice respectively) and studied 5 months later, when they display synaptic deficits and higher GFAP levels but before amyloid plaque and Tau deposition." (PMID 30322407, 2018). "GFAP expression in the DG of older iTG rats that had repeated peripheral infections also correlated with high amyloid plaque pathology (Pearson r = 0.586, p < 0.0001), when compared to 18-month TG rats without infection." (PMID 30405400, 2018). "We have also recently reported the use of UV-denaturation assay to probe the mechanism of amyloidosis of α-synuclein, glial fibrillary protein (GFAP), and human lysozyme." (PMID 30065161, 2018). "AD patient brains have shown hypertrophic astrocytes clustering around amyloid plaques, upregulation of astrogliotic marker GFAP in brain homogenates, and elevated levels of GFAP in the CSF of AD patients." (PMID 27709751, 2016). "We have examined the same tissues by immunostaining with GFAP astrocyte-specific antibodies and detected the presence of astrocytes around amyloid plaques." (PMID 24240735, 2014). "Compared with mice on the control diet, VDM-fed wild type and AD transgenic mice displayed improved learning and memory, had significantly reduced amyloid plaque load and glial fibrillary acidic protein, and elevated interleukin-10 in the brain." (PMID 24204618, 2013). "Amyloid plaques in human AD and in AD mouse models are surrounded by reactive astrocytes with an increased GFAP expression." (PMID 22912745, 2012). "This treatment with nicotine also resulted in less glial fibrillary acidic protein- (GFAP-) immunoreactive astrocytes around the amyloid plaques and increased numbers of α7 nAChR in the cortex of APPswe mice." (PMID 21253523, 2010). "Recent data support a central role for astrocyte dysfunction early in AD pathogenesis, for example, via an association of astrocyte-enriched SNPs with early amyloid pathology, as well as changes observed to both MOA-B PET tracer positivity and plasma levels of GFAP prior to amyloid plaque formation." (PMID 40542358, 2025). "Baseline GFAP levels-particularly among those with probable amyloid pathology-may help predict cognitive responsiveness to multidomain interventions." (PMID 40681350, 2025). "The moderate positive correlation between CSF GFAP and pTau181 (ρ = 0.588) suggests that GFAP primarily reflects tauopathy-associated astrogliosis rather than amyloid pathology." (PMID 40943059, 2025). "Propionate-mediated reduction in GFAP+ reactive astrocytosis and amyloidosis is dependent on IL-17." (PMID 40359034, 2025). "Exogenous sodium propionate administration reduces GFAP+ reactive astrocytosis and amyloidosis." (PMID 40359034, 2025). "Elevations in GFAP have been observed in AD and might be due to reactive astrocytosis to parenchymal amyloid plaque." (PMID 40156276, 2025). "Overall, these results suggest that ABX- and propionate-mediated reductions in peripheral Th17 cells and IL-17 levels may lead to decreases in GFAP+ reactive astrocytosis and amyloidosis." (PMID 40359034, 2025). "For instance, CSF GFAP is a better diagnostic biomarker in AxD whereas plasma GFAP has been demonstrated to outperform CSF GFAP for differentiation of amyloid‐positive and amyloid‐negative individuals in the context of AD." (PMID 39289040, 2025). "Next, to test whether pl-GFAP levels in sCJD were significantly influenced by amyloid and tau copathologies, we stratified patients according to their A/T status." (PMID 38791145, 2024). "Blood samples were also collected for measurement of biomarkers such as NfL, GFAP, and others that may facilitate prediction of cognitive state and amyloid status." (PMID 38415908, 2024).
amyloid (continued). "By assessing the relationship between GFAP and amyloid protein in the body, researchers discovered that the plasma concentrations of GFAP in the positive group of patients were significantly higher than patients in the amyloid pathology group." (PMID 38288836, 2024). "This might be explained by the fact that plasma GFAP might represent an earlier marker than NfL in the AD continuum, and it has been suggested to mediate the relationship between amyloid and tau pathologies in preclinical AD subjects." (PMID 38755703, 2024). "However, the directions-of-effect with CAA pathology in amyloid-positive participants were largely consistent with our main analyses, further indicating that the association between GFAP and CAA stage depends on the presence of amyloid pathology." (PMID 39580758, 2024). "Furthermore, we observed a significant interaction between GFAP mRNA in the dlPFC and amyloid status on tau burden, indicating that amyloid status modifies the effect of GFAP expression on tau." (PMID 39580758, 2024). "It is possible that differential metabolism of tryptophan after abx treatment may be the mechanism reducing GFAP + astrocyte inflammatory activity and amyloidosis in our model." (PMID 37415149, 2023). "However, co-analysis of GFAP+ astrocytes with X34+ amyloid plaques or CAA revealed that although there was a strong response of GFAP+ astrocytes surrounding remaining plaques in astrocytes without APOE4, there was less GFAP+ astrocyte reactivity engaging CAA." (PMID 36922879, 2023). "Finally, clinicians should be aware that in non-AD groups, especially those in which co-existence of AD pathological change is a common finding, such as CBS and DLB, amyloid co-pathology significantly influences plasma p-tau181 and GFAP levels." (PMID 36221099, 2022). "P2Y12R-positive microglia and GFAP-positive astrocytes constantly existed in AppNL-F/NL-F mouse brain regions with amyloid pathology but were not overtly associated with these plaques, unlike dense-core plaques in APP23 mice." (PMID 33644757, 2021). "However, we know from our previous study in the same cohort of mice that ES exposure had age-dependent effects on hippocampal amyloid load, and we in fact find ES-induced differences in GFAP coverage when normalizing to the appropriate pathology readout." (PMID 32197653, 2020). "This might partly reflect the response of both CD68 and clustered GFAP signal to amyloid plaque buildup, perhaps pointing towards coordination of microglial and astrocytic phagocytosis, as reactive astrocytes are also capable of internalizing Aβ." (PMID 32197653, 2020). "In addition, increased thioflavin S‐positive amyloid plaques as well as GFAP‐positive gliosis around the plaques were detected in the congenic mice, supporting our notion that amyloid‐induced neuritic/astrocytic changes were augmented in the congenic mice." (PMID 29311134, 2018). "In a recent study of amyloid-induced inflammatory responses in the rat retina, induced inflammatory responses were characterized by increases in markers for microglia and astrocytes (ionized calcium-binding adaptor molecule 1 (Iba-1), GFAP and nestin)." (PMID 23819902, 2013). "Similarly, astrocyte activation, measured via plasma GFAP, may serve as a link between amyloid burden and tau pathology." (PMID 40640892, 2025). "Furthermore, increased GFAP expression does not appear to be linked to tau positivity in the absence of amyloid pathology, potentially reflecting astrocytic responses to extracellular amyloid plaques vs intracellular neurofibrillary tangles." (PMID 39580758, 2024). "As such, amyloid-positive individuals with high GFAP expression displayed a greater level of tau burden than amyloid-negative individuals, supporting the notion that astrocyte reactivity may serve as an intermediary between amyloid and tau pathology." (PMID 39580758, 2024).
amyloid (continued). "In addition, we observed an increase of about 70% in FABP7 staining intensity in GFAP+ astrocytes located in the vicinity of amyloid plaques (within 50 μm from the edge of a plaque) when compared to non-plaque-associated astrocytes (located at a distance > 50 μm from the edge of a plaque)." (PMID 37688656, 2024). "Furthermore, we also validated our findings by immunostaining, wherein we demonstrated increased co-localization of GFAP positive astrocytes with the two varieties of neurotoxic amyloids- Aβm0C64 & Aβ 1-42, thus underscoring the role of astrocytes in morphine-induced amyloidosis." (PMID 34527417, 2021). "Moreover, overexpression of CCL2 driven by GFAP promoter in APP/CCL2 mice enhanced amyloidosis, increased microglial Iba-1immunoreactivity, and decreased cognition while APP/PS1/CCL2 null mice also displayed increased levels of Aβ oligomers and worsening of cognitive dysfunction." (PMID 32508844, 2020). "This study aimed to investigate serum levels of NfL, glial fibrillary acidic protein (GFAP), and peripherin (PRPH) in patients with ATTRV30M amyloidosis and pre-symptomatic gene carriers, compared with controls." (PMID 42259879, 2026). "A quantitative image analysis of brain tissues stained with anti-GFAP and anti-CD45 antibodies indicated that reduction of amyloid plaques in the brains of immune 3xTg-AD mice led to less astrocytosis (P<0.05) and microglial activation (P<0.001), respectively." (PMID 18461171, 2008). "Our findings indicate that fullerenol administration, but not fullerene, significantly reduced amyloid plaque burden and prevented an increase in GFAP-positive cells in the cortex and hippocampus of mutants." (PMID 40722938, 2025). "We previously found that ABX treatment reduces GFAP+ astrocytes in male APPPS1-21 mice at 9 weeks and 3 months of age, suggesting that the GMB plays a role in regulating reactive astrocytosis in response to amyloidosis." (PMID 40359034, 2025). "Plasma GFAP distinguished individuals with ongoing brain amyloid deposition (Aβ positive) from those with relatively low amyloid deposition (Aβ negative) compared to p-Tau 181, p-Tau 231, and NFL." (PMID 40690136, 2025). "In an alternate model of amyloidosis, the removal of APOE4 reduced GFAP reactivity." (PMID 38891941, 2024). "Low GFAP was expressed and no amyloid plaques were detected in the cortices of their age-matched WT littermates." (PMID 37433857, 2023). "In a cohort of Karolinska memory clinic patients, plasma GFAP levels correlated significantly with PET-detected amyloid deposits, but not with measure of pTau in CSF, whereas plasma pTau isoforms were associated with both measures of amyloid and tau pathology." (PMID 37296589, 2023). "In the absence of IP-MS Aβ measures, GFAP is the best predictor of amyloidosis at the preclinical stage of AD and, in combination with p-tau181, best predicts amyloidosis at the symptomatic phase of the disease." (PMID 35130933, 2022). "In studies where IP-MS Aβ has not been included, GFAP has emerged as the principal candidate for amyloidosis." (PMID 35130933, 2022). "Therefore, our data suggest that although amyloidosis on its own may not cause elevated plasma GFAP in mice, combining amyloidosis with factors that reduce vascular resilience, such as apoA-I deficiency, may better recapitulate changes in plasma GFAP observed in human AD subjects." (PMID 33678186, 2021). "SOCS3 reduces GFAP and STAT3 expression in APP mice, even around amyloid plaques (star)." (PMID 30322407, 2018). "Whereas sleep fragmentation and hypoxia appear sufficient to drive astrocytic reactivity, light-induced circadian fragmentation did not further increase GFAP in the context of amyloid pathology, pointing instead to microglia as the more responsive glial population under these conditions." (PMID 41256678, 2025).